AGBL5 (AGBL carboxypeptidase 5)
Description:
Metallocarboxypeptidase that mediates deglutamylation of tubulin and non-tubulin target proteins. Catalyzes the removal of polyglutamate side chains present on the gamma-carboxyl group of glutamate residues within the C-terminal tail of alpha- and beta-tubulin. Cleaves alpha- and gamma-linked polyglutamate tubulin side-chain, as well as the branching point glutamate. Also catalyzes the removal of alpha-linked glutamate residues from the carboxy-terminus of alpha-tubulin. Mediates deglutamylation of nucleotidyltransferase CGAS, leading to CGAS antiviral defense response activation.
Synonyms: CCP5; FLJ21839; RP75
Tractability: Small molecule: a structure with a bound ligand is known. PROTAC: ubiquitination databases record sites on it.
Gene: Protein-coding gene on chromosome 2 (27,042,364 to 27,070,622, forward strand). Ensembl gene ENSG00000084693.
Subcellular location: Cytoplasm, cytosol; Nucleus; Cytoplasm, cytoskeleton, spindle; Midbody
Subcellular location (Human Protein Atlas): Cytokinetic bridge; Primary cilium; Basal body; Centriolar satellite; Microtubules
Pathways (Reactome):
Metabolism of proteins: Carboxyterminal post-translational modifications of tubulin
Gene Ontology:
Molecular function: metallocarboxypeptidase activity; tubulin binding; zinc ion binding
Biological process: defense response to virus; proteolysis
Cellular component: cytoplasm; midbody; mitotic spindle; nucleus; cytosol; microtubule cytoskeleton; spindle
Genetic constraint (gnomAD): Loss-of-function variants: 51 observed, 90.87 expected, observed/expected ratio (o/e) 0.56, 90% interval 0.45 to 0.71. The upper end of that interval is the gene's LOEUF score, 0.71, which puts it in group 2 of 6, group 1 being the genes least tolerant of losing a copy. Missense variants: 1,031 observed, 1,215.7 expected, observed/expected ratio (o/e) 0.85, 90% interval 0.81 to 0.89. Synonymous variants: 446 observed, 462.42 expected, observed/expected ratio (o/e) 0.96, 90% interval 0.89 to 1.04.
Gene-disease validity (ClinGen):
ClinGen rates the evidence that AGBL5 causes each of these diseases.
inherited retinal dystrophy (autosomal recessive): Definitive. An instance of retinal degeneration that is caused by an inherited modification of the individual's genome.
Homologues: Orthologues: chimpanzee AGBL5 (99% identical), macaque AGBL5 (98% identical), dog AGBL5 (90% identical), rabbit AGBL5 (90% identical), pig AGBL5 (88% identical), guinea pig AGBL5 (88% identical), mouse Agbl5 (88% identical), rat Agbl5 (88% identical), zebrafish agbl5 (54% identical). Paralogues in human: AGBL2 (19% identical), AGBL3 (19% identical), AGTPBP1 (17% identical), AGBL1 (16% identical), AGBL4 (16% identical).
Diseases named in the same sentence as AGBL5 in open-access papers:
AGBL5 is named in the same sentence as 31 diseases in open-access papers, as found by Europe PMC text mining. Sharing a sentence is not in itself a finding about the gene and the disease. The quoted sentences say what the papers report.
ciliopathy (7 papers, 2017 to 2025). A genetic disorder of the cellular cilia or the cilia anchoring structures, the basal bodies, or of ciliary function. "We herein describe two patients with URP and possible ciliopathy, associated with two novel variants in AGBL5 and one novel variant in RPGR, respectively." (PMID 35892439, 2022). "Consequently, mutations in AGBL5 may lead to ciliopathy phenotypes with extra-retinal manifestations." (PMID 39672920, 2025). "AGBL5 was proposed as a candidate gene for human ciliopathies." (PMID 40926193, 2025). "Given the importance of AGBL5/CCP5 in maintaining proper tubulin glutamylation in ciliated cells, and considering the key role of the latter in sensory perception, it is tempting to speculate that mutations in AGBL5 could lead to ciliopathy phenotypes with syndromic extraretinal manifestations." (PMID 39672920, 2025).
retinitis pigmentosa (7 papers, 2020 to 2025). Retinitis pigmentosa (RP) is an inherited retinal dystrophy leading to progressive loss of the photoreceptors and retinal pigment epithelium and resulting in blindness usually after several decades. "To date, pathogenic variants in AGBL5 have been associated only with isolated retinitis pigmentosa (RP)." (PMID 39672920, 2025). "AGBL5: recently described as underlying syndromic cases of combined retinitis pigmentosa and hearing loss." (PMID 40149483, 2025). "While mutations in AGBL5 are most known for causing retinitis pigmentosa, it has also been suggested that they lead to intellectual disability." (PMID 39210637, 2024). "Through the co‐segregation verification and clinical phenotypic analysis, we consider AGBL5 gene mutations as candidate pathogenic variants in this family of retinitis pigmentosa." (PMID 32100970, 2020). "Mutations in AGBL5, which encodes the deglutamylating enzyme CCP5, have been linked to retinitis pigmentosa, suggesting that altered polyglutamylation may cause photoreceptor cell degeneration, though the underlying mechanisms are unclear." (PMID 39528655, 2024). "Indeed, as mutation in AGBL5, coding the deglutamylase CCP5, leads to retinitis pigmentosa in humans, it suggests that perturbation of glutamylation could lead to drastic consequences on photoreceptor survival." (PMID 39528655, 2024). "The importance of tubulin PTMs in photoreceptor maintenance has recently been highlighted by the fact that mutations of AGBL5, coding the deglutamylase CCP5, lead to retinitis pigmentosa in human." (PMID 39528655, 2024). "Next, we wanted to assess whether the observed distribution of tubulin PTMs is conserved in human retina, as mutations of AGBL5, coding for CCP5, lead to retinitis pigmentosa in human." (PMID 39528655, 2024). "AGBL5, the gene coding CCP5, is a retinitis pigmentosa causative gene." (PMID 37226238, 2023). "There are few reports of retinitis pigmentosa caused by mutation of AGBL5 gene, and only a few reports indicate that homozygous nonsense mutation of AGBL5 gene can cause non‐syndromic retinitis pigmentosa." (PMID 32100970, 2020).
hearing loss (2 papers, 2025). "In this study, we demonstrate that biallelic pathogenic variants in AGBL5, previously linked only to isolated RP, can induce a syndromic Usher-like phenotype, encompassing both RP and hearing loss." (PMID 39672920, 2025). "The complex relationship between genotypic variations in AGBL5 and the phenotypic expression of hearing impairment emphasizes the need for further investigations in larger cohorts to elucidate the underlying mechanisms." (PMID 39672920, 2025).
Leber congenital amaurosis (2 papers, 2021 to 2024). Leber congenital amaurosis (LCA) is a retinal dystrophy defined by blindness and responses to electrophysiological stimulation (Ganzfeld electroretinogram (ERG)) below threshold, associated with severe visual impairment within the first year of life. "The confirmed genetic diagnosis in the retinal dystrophy group included RP in three (AGBL5, RBP3, and PRPF8), Leber congenital amaurosis in one (RPE65) and gyrate atrophy in one (OAT)." (PMID 33494148, 2021).
retinal degeneration (2 papers, 2024 to 2025). Degeneration of the retina. "Therefore, reducing initiating glutamylases such as TTLL5, which has also been associated with hyperglutamylation and retinal degeneration, could restore the balance of glutamylation in AGBL5 deficient cells." (PMID 40926193, 2025). "Therefore, AGBL5 and/or hyperglutamylation could be explored as targets for therapy in patients with defects in this gene, or other forms of retinal degeneration that involve changes in basal body or ciliary glutamylation levels." (PMID 40926193, 2025).
retinal disease (2 papers, 2025). "Hearing loss has not been reported in AGBL5-caused retinal disease." (PMID 39672920, 2025). "Due to the advances in use of antisense oligonucleotides (ASOs) in treatment of rare disease, including rare retinal diseases, we were interested to test whether an siRNA approach to reducing TTLL5 levels could rescue the ciliogenesis and glutamylation defects observed in AGBL5−/− clones." (PMID 40926193, 2025).
Retinal dystrophy (2 papers, 2021 to 2023). Retinal dystrophy is an abnormality of the retina associated with a hereditary process. "Additional examples include the animal models of MICU2 and AGBL5 deficiency identified, respectively, in family F5563 with severe neurodevelopmental disorder and family F2707 with non-syndromic retinal dystrophy." (PMID 37644014, 2023).
autosomal recessive retinitis pigmentosa (1 paper, 2025). Autosomal recessive retinitis pigmentosa (RP) is an autosomally recessive inherited retinal dystrophy leading to progressive loss of the photoreceptors and retinal pigment epithelium and resulting in blindness usually after several decades. "Pathogenic variants in the AGBL5 gene (OMIM * 615900), also known as CCP5, have been reported to cause isolated autosomal recessive retinitis pigmentosa (arRP) in different populations." (PMID 39672920, 2025).
cone-rod dystrophy (1 paper, 2025). Inherited retinal dystrophies that belong to the group of pigmentary retinopathies. "Although mutations in TTLL5 cause cone-rod dystrophy in humans and reduced male fertility we hypothesized that on an AGBL5 knockout background, reduction in TTLL5 levels could be potentially therapeutic." (PMID 40926193, 2025).
deafness (1 paper, 2025). An inherited or acquired condition characterized by the complete loss of the ability to hear from one or both ears. "Interestingly, his brother (II.1), besides being homozygous for the AGBL5 variant, also harbored a homozygous, likely pathogenic, nonsense variant (NM_016239.4:c.7121C>G, p.(Ser2374Ter)) in MYO15A, a gene associated with profound, congenital, nonsyndromic deafness (OMIM * 602666)." (PMID 39672920, 2025).
retinal ciliopathies (1 paper, 2025). "One of the genes associated with retinal ciliopathies in humans is ATP/GTP Binding Protein Like 5 (AGBL5; OMIM 615900; Ensembl ID ENSG00000084693), also known as Cytosolic Carboxypeptidase-Like Protein 5 (CCP5)." (PMID 40926193, 2025).
teratozoospermia (1 paper, 2022). "Several teratozoospermia-associated gene mutations, including F-box only protein 43 (FBXO43), armadillo repeat-containing protein 2 (ARMC2), SEPTIN12, and AGBL carboxypeptidase 5 (AGBL5), have been identified by measuring exonic mutations in blood samples using whole exome sequencing technology." (PMID 36292606, 2022).
Usher syndrome (1 paper, 2025). A syndromic diseae characterized by the association of sensorineural deafness (usually congenital) with retinitis pigmentosa and progressive vision loss. "The identification of AGBL5 as a causative gene of Usher-like phenotypes advances our understanding of the intricate manifestations of Usher syndrome and highlights the pathogenic role of ‘tubulin code’ perturbations in sensory ciliopathies." (PMID 39672920, 2025).
viral infection (1 paper, 2025). "AGBL5 deglutamylation activity in particular, is required to activate cyclic GMP-AMP synthase and subsequent interferon response during viral infection." (PMID 40926193, 2025).
infection (2 papers, 2019 to 2023). The state of being infected such as from the introduction of a foreign agent such as serum, vaccine, antigenic substance or organism. "In addition, a number of genes associated with GTPase activities, which included GIMAP2, RACGAP1, AGBL5 and RAP1GDS1, were down-regulated during the early phase of infection." (PMID 30789917, 2019).
retinal disorder (2 papers, 2025). Any disease or disorder of the retina. "In conclusion, the analysis of the sensory phenotype of patients with biallelic variants in AGBL5 has expanded our understanding of the gene’s implication in the context of inherited retinal disorders." (PMID 39672920, 2025).
cancer (1 paper, 2024). A tumor composed of atypical neoplastic, often pleomorphic cells that invade other tissues. "The analysis revealed a distinct overexpression of a single isoform for several genes, namely AGBL5, BOP1, FTSJ3, LGALS1, and NOP58, suggesting a dominant role of these isoforms in the cancer phenotype." (PMID 39001461, 2024). "Among the most significantly downregulated genes in tumor samples were AGBL5, SECISBP2, and PLTP, which are involved in protein deglutamylation, selenoprotein synthesis, and lipid metabolism, respectively, and their downregulation may impact platelet function and stability in cancer." (PMID 39001461, 2024).
AGBL5 also shares sentences with these, for which no sentence is quoted: Hydrocephalus (3 papers); autosomal dominant polycystic kidney disease (1); Fuchs corneal dystrophy (1); galactosemia (1); gyrate atrophy (1); Hearing impairment (1); Immune System Disease (1); infectious disease (1); Intellectual disability (1); male infertility (1); neuroblastoma (1); neurodevelopmental disorder (1); Renal cyst (1); tumor (1).